CD4 (CD4 molecule)
Diseases named in the same sentence as CD4 in open-access papers (continued):
Sharing a sentence is not in itself a finding about the gene and the disease.
tumor (continued). "In addition to the direct anti-tumor effect of Vγ9Vδ2 T cells, the numbers of CD4+ T and CD8+ T cells could also get increased after the allogeneic Vγ9Vδ2 T cells were transferred into the patients, as shown in another study of cholangio-carcinoma." (PMID 33664732, 2020). "One of such immune subsets is the tumor-associated macrophages (TAMs) which are polarized into M2 macrophage phenotype by IL-10, TGF-β, IL-4, or IL-13 present in the TME, and drive tumor progression by supporting angiogenesis and recruitment of CD4+FoxP3+ T regulatory cells (Tregs)." (PMID 33117354, 2020). "In the tumor, however, they were significantly higher in the infiltrated CD4+ and CD8+ T cells of Lsp1 KO mice than in those of WT mice, suggesting that Lsp1 deficiency increases antitumor immunity by inducing TNF-α+ and IFN-γ+ expression in tumor-infiltrating T cells." (PMID 33020243, 2020). "We could confirm that CD4 T cells infiltrated in tumors; however, even a higher level of CD4 T cells was found in the central cancer stroma and along the invasive margins of the tumor, which possibly indicated an impeded infiltration into the tumor." (PMID 32923385, 2020). "Indeed, CD8+ and CD4+ T cells play a critical role in tumor rejection response." (PMID 32370748, 2020). "Also, regulatory T cells (Tregs) are committed to survive and proliferate in such a hostile milieu like tumor microenvironment because they display and exploit both glycolysis and fatty acid synthesis/oxidation, allowing them to predominate over CD4/CD8+ T cells mainly relying on the glycolysis." (PMID 32185131, 2020). "Therefore, BIRC5 may also regulate tumor cell biological process, thus affecting the prognosis of chRCC via CD4+ T cells." (PMID 32662515, 2020). "Together, the evidence above indicates that CD4+ T cells play a key role in cancer immunity, which provides a strong rationale to explore whether genetic engineering can be employed to optimize their contribution to effective tumour protection." (PMID 32708397, 2020). "The unprecedented strong stimulation of tumor-specific CD4+ T cells that were obtained with our approach let us hope that this will help in identifying a constellation of MHC class II-restricted tumor antigens for more potent next generation anti-tumor vaccines." (PMID 33138029, 2020). "Taken together, increased iron concentration in the tumor milieu caused by intravenous iron supplementation hampers activation, expansion, survival and functionality of the two key effectors of anti-tumor immunity, CD8+ cytotoxic T cells and CD4+ T helper cells." (PMID 33344239, 2020). "Likewise, tumor-associated CD103+CD4 TRM have been described to be highly enriched for tumor-specific T cells and suppress tumor growth through the secretion of TNF-α and IFN-γ or direct killing of tumor cells." (PMID 32973794, 2020). "However, in tumor-bearing animals, P2Et decreased the number of intratumor myeloid-derived suppressor cells (MDSCs) and increased the number of CD4+ and CD8+ T cells, suggesting a role in the modulation of the immune response, which is different in relation to the presence or not of tumors." (PMID 33312174, 2020). "In addition, ATP may fuel a direct antitumor immune response by depleting Treg cells via P2X7R-mediated cytotoxicity or via stimulation of DCs, thus triggering IL-1β release and potentiating tumor antigen presentation to CD4+ and CD8+ lymphocytes." (PMID 33212982, 2020). "Therefore, for future studies, simultaneous (multiplex) staining for PD-L1 and CD4 could result in improved accuracy of tumour PD-L1 assessments in biopsy samples." (PMID 32433601, 2020). "Therefore, it will not be favorable to use P-gp-inhibitors in this scenario, as this might reduce the cytotoxic potential of these tumor infiltrating anti-cancer Th1 and Th17 CD4+T cell phenotypes." (PMID 32195185, 2020).
tumor (continued). "In addition to these roles, P2X7 receptors also modulate the tumor microenvironment wherein blockade of the receptors through systemic administration of A740003 showed an increase in CD4+ cells but with diminished expression of ectonucleotidases, CD39 and CD73." (PMID 33584298, 2020). "Through further analysis of tumor infiltrating immune cells, it could be found that in patients with high MAPS presented significant lower abundance of CD4+ and CD8+ T cells infiltrate compared with high-risk group, and these cells have also been proved to be closely related to tumor prognosis." (PMID 33679869, 2020). "In addition, IFN-γ production by CD4+ T cells activated by UM vaccines, promoted an antitumor response by inhibiting neovascularization and tumor cell proliferation, as well as upregulating tumor-expressed MHC molecules." (PMID 32992823, 2020). "Poor prognosis is associated with the accumulation of myeloid-derived suppressor cells, tumor-associated macrophages, CD4+/CD25+/FOXP3+ immune-suppressive T-cells(T-reg), exhausted Th1 CD4+, CD8+ T-cells, dysfunctional NK cells and the expansion of Th2 CD4+ T-cells." (PMID 33086471, 2020). "Considering that flow cytometry of distant tumour-free liver samples demonstrated similar linear relationships between CD4+ T cells, CD4+FoxP3− T helper cells, the CD8/CD4 ratio, and the percentage of dHGP scored at the tumour–liver interface, HGPs could, at least in part, be host-determined." (PMID 32418992, 2020). "Furthermore, upon examining the composition of the immune cells, including natural killer (NK) cells, lymphocytes, eosinophils, basophils, CD4+ T cells, and CD8+ cells, in the BALF, antitumor NK cells and CD8+ T cells were reduced, and tumor‐promoting neutrophils and CD4+ T cells were increased." (PMID 34766117, 2020). "In addition, similar to CD4+CD25+ Tregs, we found that tumour-infiltrating CD73+Vδ1 T cells could suppress IFN-γ secretion from CD4+ T cells and Perforin and Granzyme B secretion from CD8+ T cells." (PMID 32345959, 2020). "Yet, the new subset CD4-GZMA cell may exert significant levels of anti-tumor immunity." (PMID 33043022, 2020). "This may be achieved using the expression of CD39 on tumor-infiltrating CD4+ T cells." (PMID 33425717, 2020). "Additionally, studies that looked at DC MHC-II expression found that MIF promotes downregulation of MHC-II, which further suggests that MIF may also impair tumor antigen presentation of DCs to CD4+ T cells." (PMID 33324425, 2020). "PD-1 overexpression in TILs affects the prognosis of several solid cancers, and the increased PD-1 expression among tumor-infiltrating CD4+ TLs reflects a usually high level of PD-1 expression on Tregs, which may represent a large proportion of intra-tumor CD4+ TLs." (PMID 33381116, 2020). "A comparable result could be observed in high- and low-expression groups of CD8A, T cells CD8 (in 31 tumor types), T cells CD4 memory activated (in 26 tumor types), Macrophages M1 (in 26 tumor types), Macrophages M0 (in 24 tumor types) were also identified as differential infiltrated TIL types." (PMID 33585244, 2020). "Analysis of the RNA profile of CD4+ CD146+ T cells from peripheral blood shows high levels of genes associated with Th17 cells (IL-17A, ROR-γ, IL-22, IL-26, IL-23R, CXCL-13, IL1-β, GM-CSF) which exacerbate inflammatory reactions and indirectly promote tumor progression." (PMID 33352759, 2020). "Thus, our data revealed that the tumor microenvironment of OC could promote the glycolysis metabolism of human CD4+ T cells." (PMID 33102225, 2020). "In addition, tumor-infiltrating γδ T cells could significantly inhibit the maturation of CD4+ T cells." (PMID 33664732, 2020). "Besides supporting CD8 T cells, CD4 T cells may directly lyse tumor cells in an MHC-II dependent manner through the secretion of perforin and granzyme." (PMID 33381115, 2020).
tumor (continued). "Hence, the application of radiofrequency energy over the HCC tumour facilitates the release of DAMPs with subsequent increase in peripheral and tumour infiltrating CD4+, CTLs and NK cells, which shift the scale of balance towards the antitumour immune response rather than cancer progression." (PMID 32456200, 2020). "Interestingly, the higher number of circulating CD4+ and CD8+ T cells was associated with higher pre-treatment infiltration of these cells in the tumor microenvironment of responsive patients compared to non-responders, as evaluated by IHC in both primary and metastatic lesions." (PMID 32770287, 2020). "We assumed the CD4-GZMA cell type might be a key point in anti-tumor immune responses in HCC." (PMID 33043022, 2020). "Furthermore, an unpublished study from the Würzburg group has shown that the number of tumor-infiltrating CD4+ and CD8+ T-lymphocytes are stage-independent prognostic indicators in patients with ACC and that glucocorticoid excess is associated with T-cell depletion and unfavorable prognosis." (PMID 32183347, 2020). "Moreover, several studies demonstrated that Tregs derived from both blood and tumor of CRC patients were able to suppress the proliferation of autologous CD4 and CD8 T cells, and that the frequency of Tregs was negatively correlated with the expression of IFN-γ and IL-2 in the tumors." (PMID 32210966, 2020). "Thus, an immune cell composition of CD4+CD68+CSF1R+ could exert strong anti-tumor effects with great cooperativity between these immune factors." (PMID 32850346, 2020). "Moreover, after CD4+ T cells are activated, cytotoxic T lymphocytes (CTLs) can be activated by activated CD4+ T cells through various mechanisms to maintain and enhance the anti-tumor response of CTLs in tumours." (PMID 33170901, 2020). "However, lack of direct evidence of influence of tumor cell-associated ICOSL on CD4+ and CD8+ T cells is a limitation for this current study, and more detailed molecular study is needed in the further study." (PMID 31998801, 2020). "Therefore, CD4+ TILs in the TS may have the opposite effect on tumour immunity, and many previous studies could support this conclusion." (PMID 33170901, 2020). "Therefore, tumor-induced CD4+CD25− T cells were more prone to conversion." (PMID 32456622, 2020). "Furthermore, CD4+ T cells have been shown to mediate direct cytotoxicity against tumor cells through increased production of interferon gamma (IFNγ) and tumor necrosis factor (TNFα in both preclinical models and patient-derived CD4+ T cells." (PMID 33383959, 2020). "Flow cytometric analysis revealed that there was an increase in percentage of total CD3+ T cells and in CD8+/CD4+ T cell ratio in TUBO tumours from WT BALB/c mice compared to TUBO tumours from BALB/c-NeuT mice, suggesting that T cells may contribute to the tumour regression in WT BALB/c mice." (PMID 32127568, 2020). "Moreover, Bregs might disable the cellular immune response against the tumor by promoting the conversion of CD4+/CD25− T lymphocytes to FoxP3+ Tregs, thereby, enabling tumor growth and the development of metastasis." (PMID 32602047, 2020). "However, the discovery of regulatory T cells (Treg) has markedly changed conventional speculation regarding the role of CD4 + T lymphocytes in anti-tumor immunity." (PMID 32222891, 2020). "Moreover, we reveal MR maybe module the tumor microenvironment via promoting the T cells CD4+, DC, and NK cell infiltrated." (PMID 33193899, 2020). "However, CD4+ Th2-mediated responses may promote tumor growth via increasing angiogenesis and hampering Th1 cell-mediated immunity." (PMID 32499786, 2020). "Finally, intratumoral injection of a combination of lactate signaling pathway inhibitors gallein and ARC in 4T1 tumor mouse models, led to significant reduction in the percentage of intratumoral FoxP3+ CD4+ T cells, thus confirming the role of lactate in enhancing Treg induction." (PMID 31440253, 2019).
tumor (continued). "In addition to CD8+ T cells, we found that LTX-315 induced changes in other immune cell types in the tumor microenvironment, including CD4+ T cells and NK cells, which may also contribute important antitumor activities." (PMID 31799501, 2019). "Additionally, CD4CAR therapy might provide an added benefit of depleting CD4+ T cells and modulating the tumor microenvironment." (PMID 31413761, 2019). "These peptides, along with a number of highly specific HCC MHC-I-bound tumor peptides, contributed to the formation of a peptide cocktail to be used as the first multi-epitope, multi-target, and multi-allele cancer vaccine against HCC aimed at stimulating both CD4+ and CD8+ T cells." (PMID 31417570, 2019). "In addition, correlations between CD20+ and CD4+FOXP3+ were seen, implying their potential functional associations within the TME that may negatively impact the infiltration of immune cells into tumor areas." (PMID 31166985, 2019). "However, when correcting for background levels of tracer, we found a good agreement between the mean and maximum tumor-to-heart ratios and flow cytometric analysis of CD4+ and CD8a+, which makes sense from a physiological perspective when assessing different tumor types." (PMID 31754392, 2019). "However, the role of CD4 immunity in patients undergoing PD‐L1/PD‐1 blockade therapy remains poorly understood although extensive pre‐clinical data link CD4 responses to anti‐tumor immunity." (PMID 31273938, 2019). "Moreover, anti-CA125, anti-HER2/neu, anti-MUC1, anti-EGFR mAb treatment can circumvent the tolerance to self-antigens expressed on tumor cells as shown by the increase of the frequency of CD4+ and/or CD8+ T cells recognizing peptides derived from the target molecule in cancer patients." (PMID 31494742, 2019). "Thus, we presumed that the mechanism of AXIN2 regulating T cells CD8 and T cells CD4 memory resting might have an influence on tumor progression and metastasis." (PMID 31681739, 2019). "In addition, since tumor-derived exosomes have contrasting effects on DC function, the outcome of CD4+ T-cell response may differ depending on the model system." (PMID 31181729, 2019). "Additionally, we noted that C75 treatment skewed primary effector CD4 T cells toward a Th2-like phenotype, which could be detrimental to some immune responses, including anti-tumor T cell reactions that require IFN-γ." (PMID 31681794, 2019). "To further determine whether human TRAPs (hTRAPs) could induce human CD4+ T cells to produce IL-6, we collected hTRAPs from the culture media of 3 human tumor cell lines, A375, MDA-MB-231 and HepG2, and from the malignant effusions or ascites of 8 cancer patients." (PMID 31300052, 2019). "This suggests that the blood T-cell profile observed in high tumor burden FL patients could be at least partially reverted by rituximab-based treatment, and that anti-tumor activity could be reinforced by an increase in the number of CD4+ TCM, CD8+ TCM and CD8+ TN." (PMID 31530876, 2019). "FS with good CD4+ T cell epitopes may also elicit tumor cell killing." (PMID 31578439, 2019). "To analyze whether the levels of tumor-infiltrating Foxp3hiTbethi Tregs could be linked to a more activated tumor immune profile, we analyzed the activation status of the tumor-infiltrating CD4+ and CD8+ T cells in a cohort of 13 previously studied OPSCC tumors, of which 8 were also included here." (PMID 30658697, 2019). "It is unclear how CD8+ T cells might affect the trafficking of CD4+ T cells to the tumor site." (PMID 31112530, 2019). "Remarkably, the increased levels of CD4+CD25+ Tregs and PD-1+ T cells correlated positively to better clinical prognosis in HNSCC patients, which is different from the common observation of elevated Tregs in association with immunosuppression and poor clinical outcomes in other tumor types." (PMID 31024913, 2019).
tumor (continued). "A specific identification of each CD4+ T cell lineage should be performed to determine if the high count of CD4+ T cells in G4 contain a small number of Tregs that slightly diminishes the recruitment capacity of CD8+ T cells into the tumor, lowering its total count." (PMID 31762937, 2019). "Tumor microenvironment induces differentiation of CD4+ T cells into different subsets of T cells, mainly suppressive regulatory T cells (Treg), and T helper 17 (Th17) cells, although their exact role in tumor immunity is still under debate depending on tumor types and stages." (PMID 31024835, 2019). "In addition, PD-L1-expressing DCs may also drive the progression of naïve, PD-1-expressing CD4 Tregs to the mature, immunosuppressive phenotype, favoring co-operative impairment of anti-tumor host defenses due to co-expression of CTLA-4 and PD-1 by Tregs." (PMID 31616428, 2019). "Moreover, DC depletion in vivo lowered tumor-infiltrating CD4+ T-cell expression of CD39, CD49b, CD73, AHR, IL-17, and IL-10 in PDA suggesting that, besides driving select cytokine expression, DC promote this Tr1-like surface phenotype in PDA-associated CD4+ T cells." (PMID 30926808, 2019). "Interestingly, in contrast to the moderate in vitro cytotoxicity compared with CD8+ T cells, 19305DP-TCR-transduced CD4+ T cell alone showed efficient inhibition of tumor growth to a similar degree as that observed with 19305DP-TCR-transduced CD8+ T cells in vivo." (PMID 30626427, 2019). "However, cellular senescence and apoptosis are two types of cellular responses to DNA and cellular damage that are altered in both cancer (BACH2 repression in CD4+ T cells modulates their resistance to apoptosis demonstrating it functions as a tumor suppressor gene, in preparation) and aging." (PMID 30654767, 2019). "CD8+and CD4+ T cells, including regulatory T (Treg) and T helper 17 (Th17) T cell subsets, and have increasingly been recognized as key players in carcinogenesis particularly for their role in promotion and maintenance of an immunosuppressive and pro-tumor inflammation environment." (PMID 31311583, 2019). "GITR agonist increases activation, proliferation and effector function of CD8+ and CD4+ T cells, while decreasing intra-tumor regulatory T cells (Tregs) by depletion and Treg lineage stability alterations, thus proving effective in various preclinical tumor models." (PMID 31747946, 2019). "Also in this model A740003 treatment caused a significant reduction in tumor growth similar, if not increased, to the WT host and possibly ascribable to a rise in CD4+." (PMID 30655604, 2019). "Remarkably, compared to intact TRAPs, tumor cell lysates containing an equal amount of total protein but much more Hsp90α, or sonicated TRAPs containing an equal amount of Hsp90α, or proteinase K-treated TRAPs were much less effective in inducing IL-6 secretion from CD4+ T cells." (PMID 31300052, 2019). "Indeed, the role of CD4+ T cells in the tumor microenvironment is of growing interest as these cells have been shown to be required for efficacious anti-tumor immunity and can target tumor cells in various ways (reviewed by Borst et." (PMID 31754392, 2019). "Furthermore, a phase I/II study have shown that CD4+CD25+ Treg depletion improves the graft-vs.-tumor therapeutic effect of donor lymphocyte infusion in patients suffering from hematopoietic malignancies and relapse after standard allogeneic hematopoietic stem cell transplantation (NCT00987987)." (PMID 31134056, 2019). "Of note, mutations within the HLA class I alleles, mostly in HLA-A and HLA-C, were identified in the tumour lesion obtained from patient PanTT39, which may have given rise to preferential expansion of CD4+ T cells recognising the nominal tumour target antigen bound to HLA class II molecules." (PMID 30377343, 2019). "A single dose of about 2Gy may recruit tumor-specific CD8+ and CD4+ T lymphocytes into the tumor." (PMID 31261963, 2019).